FGFR2 (fibroblast growth factor receptor 2)
Diseases named in the same sentence as FGFR2 in open-access papers (continued):
Sharing a sentence is not in itself a finding about the gene and the disease.
cancer (continued). "We previously identified activating mutations in fibroblast growth factor receptor 2 (FGFR2) in 12% (stage I/II) to 17% (stage III/IV) endometrioid ECs and found that these mutations are associated with shorter progression‐free and cancer‐specific survival." (PMID 30537101, 2019). "It has been showed that miR-494 53, miR-381-3p 41 and miR-125b 57 directly target FGFR2 to regulate cancer progression." (PMID 31523191, 2019). "Depletion of FGFR2 in cancer cells attenuated the hypoxia-mediated cell invasion, while forkhead box O1 (FOXO1) expression increased in smooth muscle cells and cardiomyocytes under hypoxia." (PMID 30867905, 2019). "Even though FGFR2 is considered to promote growth of cancer cells per se, it has been demonstrated to be downregulated in various cancers including prostate cancer." (PMID 30837551, 2019). "Similar to the SLIT/ROBO pathway, the FGFR2 signalling pathway plays a role in cancer progression as well." (PMID 30857150, 2019). "We have chosen to investigate four genes SIRT1, FGFR2, STAT3, and RAGE which are known to be closely associated with different types of cancer and are related to pathogenetic processes." (PMID 31781300, 2019). "Of 455 440 estimated patients who died of cancer in 2019, 17 019 (3.7%) were estimated to have FGFR2 or FGFR3 alterations." (PMID 31755953, 2019). "High FGFR2 was associated with increased frequency of vascular invasion (p=0.047), high MET with distal location of the cancer (p=0.012) and low KRAS with presence of distant metastasis (p=0.022)." (PMID 31602266, 2019). "In agreement with the proposed central role of the aberrant splicing in tumorigenesis, the altered splicing of FGFR2 and the consequent appearance of the mesenchymal FGFR2c isoform was observed in several carcinomas." (PMID 31261937, 2019). "There are 36 protein kinases in the Cancer Gene Census; seven of them (EGFR, ERBB2, BRAF, FLT3, PRKACA, LCK, and FGFR2) had enriched PTM/mutation domains in our study." (PMID 29695735, 2018). "Since confocal microscopy confirmed that scFvF7-Fc was effectively internalized by cancer cell lines with FGFR2 overexpression, we conjugated it with the cytotoxic drug vcMMAE in order to produce an antibody-drug conjugate." (PMID 29420662, 2018). "BAY 1179470 interacts with FGFR2 on the surface of the cancer cells overproducing this receptor and induces FGFR2 internalization and the subsequent lysosomal degradation." (PMID 30577533, 2018). "The scFvF7-Fc antibody construct presented the highest affinity for FGFR2, with a KD of 0.76 nM, and was selectively internalized into cancer cells overexpressing FGFR2, Snu-16 and NCI-H716." (PMID 29420662, 2018). "To summarize, we have generated a high-affinity scFvF7-Fc format from the scFvF7 antibody fragment specific for the extracellular domain of FGFR2, which undergoes rapid internalization into cancer cells upon binding to FGFR2." (PMID 29420662, 2018). "Among the 27 somatic mutations, 24 were restricted to the brain metastases, of which 4 affected cancer-related genes (i.e., FGFR2, MAP2K4, ATR and PIK3CA)." (PMID 29755676, 2018). "While needing to be confirmed, co-splicing correlations suggest an underlying coregulation of the alternative splicing of FGFR2 and CASC4, modulated by risk SNPs for cancer." (PMID 30545302, 2018). "BAY 1187982 demonstrates a high cytotoxicity against cancer cells producing FGFR2, and the cytotoxic activity correlates well with the level of FGFR2 on the cell surface, underscoring the relevance of receptor trafficking." (PMID 30577533, 2018). "Although correlations were smaller than in previous cases, we found that the top 20 genes that co-spliced with FGFR2 significantly enriched the pathway Central carbon metabolism in cancer (adjusted-P = 1.57 × 10− 2)." (PMID 30545302, 2018). "Targeting the FHF4/FGFR2 axis that mediates the CAF-cancer stem cell signaling prevented the CAFs from inducing cancer stem cells." (PMID 30380628, 2018).
cancer (continued). "In this review, aberrant splicing events in cancer-associated genes, namely BCL2L1, FAS, HRAS, CD44, Cyclin D1, CASP2, TMPRSS2-ERG, FGFR2, VEGF, AR and KLF6, will be discussed." (PMID 30463359, 2018). "A second set consisted of an additional 15 cancer-related genes (Nf1, Mki67, Mllt4, Fgfr2, Ctnnb1, Fat1, Clp1, Fat4, Arid1a, Nat1, Nat2, Setd2, Impg1, Nbas and Npat)." (PMID 29925311, 2018). "Treatment with regorafenib effectively inhibited cellular growth and phosphorylation of FGFR2 and its downstream signaling molecules in a dose‐dependent manner and selectively in FGFR2‐amplified cancer cell lines." (PMID 29573334, 2018). "FGFR2 as one of the important factors on the surface of CAFs is overexpressed in some human cancers including stomach, pancreas, and breast." (PMID 29071223, 2017). "FGFR2 has been proved to be associated with many diseases, especially the relationship between FGFR2 and cancer, which has become a hot research topic in recent years." (PMID 27966449, 2017). "A meta-analysis including various types of cancers showed that FGFR2 amplification significantly correlated with poor survival." (PMID 28056982, 2017). "The transcript expression levels for FGFR2 showed the highest values for the complex carcinoma samples." (PMID 28945747, 2017). "FGFR2 and FGFR3 mutations have been identified among 17.6 % of HPV-positive tumors, and both mutations have been described in several cancer types, and are sensitive to FGFR inhibitors." (PMID 27154171, 2016). "Based on these results, we conclude that ARQ 087 inhibits the FGFR signaling pathway in these FGFR2 over-expressing cancer cells." (PMID 27627808, 2016). "FGFR1 and FGFR2 are the members of the fibroblast growth factor receptor (FGFR) family of genes with a variety of roles in cancer." (PMID 28330331, 2016). "Upregulation of FGFR2 was reported to participate in activation of these two molecules in invasive cancer cells." (PMID 26506517, 2015). "FGFR2 is found fused to various genes in different cancers where the fusion partners facilitate its constitutive activation through providing dimerization domains." (PMID 26680454, 2015). "As concerning FGFR2-IIIc isoform, we observed an increase in its expression in cancer specimens, although less marked than that of KGFR (3.3-fold, p < 0.01)." (PMID 24899248, 2014). "SDHB, FGFR2 and MUTYH (AUC = 0.68, 0.67 and 0.65, respectively) were similarly associated with diverse cancer types and thus highly variable phenotypes." (PMID 23921638, 2013). "This is reflected in various cancers, including breast, endometrial, cervical, lung, esophageal, gastric, pancreatic, and colorectal cancer, which displayed overexpression of FGFR2 IIIb." (PMID 23900974, 2013). "Two candidates with strong regulatory effects emerging from our analysis are components of growth factor receptors, and implicated in cancer development, namely ERBB2 and FGFR2." (PMID 23737949, 2013). "Overexpression of the FGFR2 IIIb isoform, also known as keratinocyte growth factor receptor, has been reported in various cancers, including breast, endometrial, cervical, lung, esophageal, gastric, pancreatic, and CRC." (PMID 22701813, 2012). "Recent studies have shown that FGFR2 plays important roles in cancer progression; therefore, it is of great interest as a novel target for cancers." (PMID 22701813, 2012). "In patients with CRC, expression of FGFR2 protein was observed in the cell membrane and cytoplasm of cancer cells." (PMID 22701813, 2012). "Recent studies have shown that gene amplification, abnormal activation, or single nucleotide polymorphisms (SNPs) of FGFR2 play important roles in cancer progression; therefore, FGFR2 has been recognized as a novel therapeutic target for cancers." (PMID 22701813, 2012). "Several kinds of molecular-targeted therapies to the FGFR2 signaling pathway have been reported in various cancers." (PMID 22701813, 2012).
cancer (continued). "In esophageal cancers, FGFR2 IIIb expression correlated with a well-differentiated cell type, and FGF7 induced cell proliferation in FGFR2 IIIb positive cancer cells." (PMID 22701813, 2012). "These hits also provide ready targets such as the FGFR2, FGFR4, known oncogenes like MET, and the activin and ephrin receptors, that are likely to be linked to the oncogenic activation of the cancer tissues in which they are expressed." (PMID 23251904, 2012). "Although principally considered a cell surface receptor, FGFR2 is also found to have nuclear localisation in a number of different breast and cancer related contexts." (PMID 21418638, 2011). "It has been reported that angiogenesis is enhanced and the expression levels of FGFR1 and FGFR2 are upregulated in cancer cells and ECs in HNSCC." (PMID 21063405, 2010). "The Cancer Pathway Finder Array analysis identified numerous cancer-associated genes exhibiting substantial over expression in trisomic BG01V APCs relative to diploid H9 APCs, including CDC25A, IGF1, MMP9, FGFR2, BRCA1, CASP8 and TERT1." (PMID 20423517, 2010). "The expression levels of FGFR1 and FGFR2 are known to be upregulated in cancer cells and ECs in HNSCC." (PMID 21063405, 2010). "Previous studies reported associations between genetic variants in the FGFR2 and FGFR4 genes and development of various cancers." (PMID 19500394, 2009). "In 39 cases (51.3%), FGFR2 immunoreactivity in cancer cells was stronger than in islets (high expression group)." (PMID 18594526, 2008). "Patients with high FGFR2 expression in cancer cells had a shorter survival time compared to those with low FGFR2 expression." (PMID 18594526, 2008). "Overall, these results indicate that FGF10 stimulates migration and invasion of cancer cells through its specific receptor, FGFR2-IIIb." (PMID 18594526, 2008). "This study integrates molecular docking, deep learning, pharmacokinetic profiling, and molecular dynamics (MD) simulations to identify potential FGFR2 inhibitors from a library of 1,350 phytochemicals derived from 51 anti-cancer medicinal plants that were traditionally used for anticancer purposes." (PMID 41615925, 2026). "Similarly, Apt-46, a newly synthesized DNA aptamer, targets FGFR2-IIIb and inhibits its activation in cancer cells." (PMID 41584352, 2026). "FGFR2, a member of the fibroblast growth factor receptor family, plays a crucial role in various biological processes, including cell proliferation, regeneration, and angiogenesis, which are hallmarks of cancer." (PMID 41415030, 2025). "The aberrant activity of CDK6, NOTCH2, and FGFR2 is described and often associated with more aggressive disease phenotypes in certain types of cancer, but it has not yet been studied in SLCT." (PMID 39592485, 2025). "The inhibitors target the ATP binding site of the FGFR2 kinase domain and inhibit cell proliferation, which suggests that FGFR2 inhibitors might be effective for cancer with not only FGFR2 fusion but also active abnormalities." (PMID 41226813, 2025). "Out of 1312 cancers with the FGFR2 abnormalities, FGFR2 inhibitors were administered in 85 cases." (PMID 41226813, 2025). "When this feedback loop is disrupted in cancer cells, FGFR2 signaling is hyperactivated, which may lead to more aggressive characteristics." (PMID 40227591, 2025). "FGFR2 can suppress cancer cell migration by modulating HIF signaling." (PMID 40393028, 2025). "Gene fusions involving FGFR2 are well-established oncogenic drivers across numerous cancer types." (PMID 41496852, 2025). "However, since normal ovarian surface epithelium does not express the IIIb isoform of FGFR2, it cannot respond to FGF7, and therefore, FGFR2-IIIb represents a rational cancer drug target." (PMID 39886662, 2024). "Notably, NOTCH1 expression was higher in benign tumors compared to precancerous and malignant tumors, whereas FGFR2 expression showed an opposite trend, with higher levels in precancerous and malignant tumors compared to benign tumors." (PMID 39063983, 2024).
cancer (continued). "For instance, the oncogene FGFR2 displays significant upregulation within cancer cells." (PMID 38395755, 2024). "Furthermore, the mean percentage of FGFR2-positive expression in malignant tumors was significantly greater than in precancerous and benign tumors (p = 0.050 and p = 0.046, respectively)." (PMID 39063983, 2024). "More research had been carried out in the treatment of FGFR2 IIIb cancers." (PMID 39596875, 2024). "The RAS/MAPK and PI3K pathways were activated in FGFR2-amplified cancers." (PMID 39596875, 2024). "Other findings, such as FGFR2 fusions, EGFR mutations, or MET exon 14 alterations, may also help refine diagnoses, as they are highly enriched in specific cancer types." (PMID 37682776, 2024). "Count of unique cBioPortal cases with FGFR2 fusions by cancer type." (PMID 39759134, 2024). "Therapies against FGFR2 are being investigated in various cancers." (PMID 39596875, 2024). "Moreover, C1GALT1 affects downstream signaling pathways and cellular behaviors, such as the epithelial-mesenchymal transition (EMT), by modifying O-glycans on key receptors like FGFR2, enhancing cancer cell invasiveness and metastatic potential." (PMID 38699634, 2024). "Notably, FGFR2 expression was higher in benign, precancerous, and malignant tumors compared to normal tissue." (PMID 39063983, 2024). "FGFR2 was expressed in the cell membrane of carcinoma cells if present." (PMID 38532197, 2024). "However, new evidence suggests a crucial role of some gene mutations (PTEN, PIK3CA, FGFR2, ARID1A, and MYC) in cancer progression from endometrial hyperplasia." (PMID 38201599, 2023). "Interestingly, short in-frame deletions in FGFR2 genetic structure were observed at a higher frequency in ICC patients as compared to other cancer types, with lung squamous carcinoma following closely." (PMID 37964396, 2023). "DNAm status in the proximity of the FGFR2 gene, such as the one observed in this study, may further influence the FGFR2 alterations in the cancer patients." (PMID 37697338, 2023). "Interestingly, alterations in the FGFR2 gene seen in several cancer types made it a target for the development of person-specific treatments." (PMID 37697338, 2023). "Therefore, knowledge of methylation status around FGFR2 of the cancer patients will help fine tune the design of the person-specific therapies further." (PMID 37697338, 2023). "Nonetheless, early clinical experiences with ATP-competitive FGFR kinase inhibitors showed how only 5% of EG cancer patients, presenting an homogeneously high-level clonal FGFR2-amplification might achieve a clinical benefit from such an approach." (PMID 36983691, 2023). "(b) What are the morphological characteristics of FGFR2-amplified carcinomas?" (PMID 36416959, 2023). "It is relevant that the often poorly treatable and aggressive subtype of diffuse carcinomas (poorly cohesive carcinomas) also shows FGFR2 amplification and that an individualized therapy option with FGFR2 inhibitors could be an option in this group." (PMID 36416959, 2023). "Thus, the isoforms of FGFR2 have been considered to have a significant impact on epithelial–stromal interactions in human cancers." (PMID 35311468, 2022). "The Asian Pan-Cancer Assay described here with the ability to detect spliced FGFR2 fusions could be helpful in helping clinicians make decisions regarding prescribing these drugs." (PMID 36213130, 2022). "Indeed, the analysis of hotspot regions in genes such as ERBB4, AKT1, FGFR2 and MLH1 underline that specific alterations in the primary tumor are extremely important for cancer prognosis prediction." (PMID 36077746, 2022). "Furthermore, nuclear translocation of FGFR1 and FGFR2 has been shown to specify the behaviour of cancer cells by regulating signalling and transcription, thus adding a further layer of complexity in the regulation of FGFR activity." (PMID 35193394, 2022). "FGFR2 plays oncogenic or antioncogenic role in different cancers." (PMID 35876658, 2022).
cancer (continued). "The 864 mutated genes (410 in newly generated subclones; 454 in eliminated subclones) were enriched for annotations related to several cancer-related pathways, including “FGFR2 mutant receptor activation”, “RAC1 GTPase cycle”, “Signaling by MAPK mutants”, etc.." (PMID 35260570, 2022). "Although poorly differentiated carcinomas were associated with peritoneal seeding (p = 0.04), FGFR2 amplification was not (p = 0.158)." (PMID 36292044, 2022). "Meanwhile, deep deletion was the dominant alteration type in LGG and MESO; however, in LGG, high expression of FGFR2 was observed, indicating that additional genetic alterations may contribute to high expression of FGFR2 in this cancer type." (PMID 33968743, 2021). "Various FGFR2 alterations have been reported in multiple cancers." (PMID 33968743, 2021). "Next, we analyzed FGFR2 CNVs across cancer types using ciBioportal." (PMID 33968743, 2021). "FGFR2 amplifications are the second most common amplifications of FGFR1-4 in cancer." (PMID 34068954, 2021). "Thus, according to MirAnalyze database, let-7a-5p, miRNA-16-5p, -21-5p share common target genes as follows: B-cell translocation gene 2 (BTG 2), and fibroblast growth factor receptor substrate 2 (FGFR2), which change their expression in cancer." (PMID 34434498, 2021). "Both antibodies stained the cell membrane of the cancer cells with FGFR2 amplification." (PMID 33633310, 2021). "For example, COADREAD and BRCA had a widespread distribution, while TCGT had a narrow spread of FGFR2 expression, which may be due to some cancer types harboring more than one subtype and therefore having more genetic diversity." (PMID 33968743, 2021). "Abnormal FGFR2 expression has been reported in various cancer types." (PMID 33968743, 2021). "We investigated changes in and links between FGFR2 mRNA and methylation status across TCGA cancers." (PMID 33968743, 2021). "First, FGFR2 mRNA expression was compared across all TCGA cancer types and exhibited a broad spectrum, indicating that a specific cancer type may have unique genetic features that drive FGFR2 expression." (PMID 33968743, 2021). "More efforts are needed to explore the methylation profiles in these 18 cancer types using more samples in the future, and in these cancers, FGFR2 methylation may also have critical functional roles on oncogenesis." (PMID 33968743, 2021). "Then, we evaluated the correlation between methylation and FGFR2 expression in 32 cancer types, the result showed that the expression levels of FGFR2 and downstream genes were mainly negatively correlated with methylation, with only a few positive correlations." (PMID 33968743, 2021). "Thus, we evaluated the methylation profiles of FGFR2 and its downstream genes in various TCGA cancers by using the GSCALite platform." (PMID 33968743, 2021). "FGF4 expression in these cancer stem cells increased sphere-formation, which could be reduced by silencing of FGFR2." (PMID 34068954, 2021). "Finally, survival association analysis was conducted to investigate the aberration patterns and potential clinical significance of FGFR2 across different cancer types." (PMID 33968743, 2021). "In this study, our two antibodies, FGFR2IIIb and FGFR2IIIc, might be useful tool for the determination of carcinomas with FGFR2 overexpression and treatment of FGFR2 inhibitors." (PMID 33633310, 2021). "Moreover, great attention has been paid on inventing FGFR2-targeted specific inhibitors for developing more precise and effective therapies for cancer." (PMID 31894857, 2020). "These highlighted FGFR2 signaling as a potential cancer therapeutic target." (PMID 34766128, 2020). "Alternative splicing and expression of FGFR2 isoforms may contribute to cancer growth in the context of epithelial to mesenchymal transition." (PMID 32522271, 2020). "Inhibition of FGFR2 signaling is a potential strategy for cancer therapy." (PMID 34766128, 2020).